SMO (smoothened, frizzled class receptor)
Diseases named in the same sentence as SMO in open-access papers (continued):
Sharing a sentence is not in itself a finding about the gene and the disease.
cancer (continued). "As GLI1 is most amenable to activation by both SMO-dependent and SMO-independent axes among the Hh pathway components, it is unsurprising that its expression is more commonly associated with poor prognosis in Hh-active cancer patients." (PMID 34572373, 2021). "The mutation of W7.55 to L in FZD2, FZD6 and SMO is associated with different forms of cancer." (PMID 30737406, 2019). "SMO, in turn, activates the glioma-associated oncogene (Gli) transcription factors, Gli1 and Gli2 9, and turns on the Shh signaling pathway, which promotes cancer cell proliferation." (PMID 31417657, 2019). "Thus, GLI inhibitors like GANT61 are advantageous in cancers where SMO contains an activating mutation or GLI activation is SHH ligand-independent and driven by e.g. KRAS mutations or by TGFβ-driven GLI2 expression." (PMID 31661013, 2019). "Various aspects of SMO are discussed, including its structure, the emergence of resistance-associated SMO mutations, and mechanisms of acquired resistance to SMO antagonists in cancer." (PMID 30558232, 2018). "However, the loss of Arl13b has also been shown to lead to increased SMO levels in the primary cilia of non-cancer cells, to ultrastructural defects in the cilium, and to aberrant polarity and proliferation of neural stem cells in the developing brain." (PMID 30410731, 2018). "Thus, agents that disrupt GLI activity have broader indications than those targeting SMO in HH-associated cancers particularly in cases of drug resistance." (PMID 29348431, 2018). "However, in many cases the somatic gain-of-function mutations in SMO occur in human cancers, making SMO inhibitors useless for therapeutic purposes." (PMID 24418624, 2014). "In addition, overexpression of SMO in cancer-associated stromal fibroblasts has been observed that in turn activates the HH signalling pathway." (PMID 23125850, 2012). "However, mutations at or downstream of SMO often render these cancers resistant to SMO inhibitors." (PMID 36556332, 2022). "Targeting CSNK1D with compounds such as SR-3029 and CK1D008 may, therefore, be a promising future strategy to treat cancer patients with acquired or a priori resistance to SMOi, and to hopefully reduce severe side effects known to be caused by established anti-SMO drugs." (PMID 34439381, 2021). "Therefore, an investigation of the mechanisms controlling the expression of SMO and additional HH pathway genes may provide valuable insight into HH signaling alterations associated with cancer development." (PMID 32784501, 2020). "Among the cancer agents that serve to inhibit the Hh pathway, the most popular target is the enzyme smoothened (SMO), a transmembrane protein that works downstream of PTCH." (PMID 40869256, 2025). "As the downstream transcriptional factor of the Hh pathway, GLI1 plays a crucial role in cancer progression and prognosis evaluation, while it is activated by an SMO-dependent or independent manner." (PMID 41323789, 2025). "Specifically, Bacteroides fragilis produces toxins that activate pathways such as NF-κB, SMO, Wnt/β-catenin, and Notch1, in addition to inducing reactive oxygen species (ROS) and DNA damage, all of which contribute to cancer progression." (PMID 40236482, 2025). "Inhibition of DYRK1B reduces GLI1 expression, offering a potential therapeutic target for GLI1-dependent cancers resistant to SMO inhibitors." (PMID 39568072, 2024). "Some of these genes are reported in other cancer-implicated signaling pathways such as Ras (SPON1), SHH (SMO), and Notch (HEY2)." (PMID 39620202, 2024). "In view of the known crosstalk between collagens and the Hedgehog (Hh) pathway in fibrosis and the role of Hh signalling in cancer cell survival, we also selected the SMO inhibitor Vismodegib as an additional drug to be tested in our experiments." (PMID 37938546, 2023). "Some cancers are able to develop mechanisms of acquired resistance to the traditional SMO antagonists detailed above." (PMID 36986819, 2023).
cancer (continued). "In our study, PTCH and SMO expression in the G4 stage of ccRCC was increased in stromal cells instead of cancer cells." (PMID 37240278, 2023). "Several clinical trials are evaluating the potential use of SMO inhibitors for a variety of cancer treatments including Cyclopamine, Saridegib, Vismodegib, Cur61414, XL-139, and Sonidegib." (PMID 37510333, 2023). "As in other targeted cancer therapies, development of drug resistance is one of the major hurdles in SMO inhibitor therapy." (PMID 35163655, 2022). "Subsequently, we investigated the mRNA expression of SMO in several cancer cell lines by quantitative real-time PCR (qRT-PCR)." (PMID 36405701, 2022). "Further studies are in progress to assure the efficacy of these GLI antagonists for the treatment of various types of cancer resistant to SMO inhibitors." (PMID 35163655, 2022). "We also compared the SMO expression levels between cancer samples and matched normal samples from 33 cancer types based on the TCGA data." (PMID 36405701, 2022). "In recent years, several SMO inhibitors have been generated and gained success as targeted cancer therapy." (PMID 35163655, 2022). "Therapeutic targeting of HH signaling has been explored for various cancer entities over the last decades with most studies focusing on the inhibition of SMO." (PMID 35990601, 2022). "Based on these findings, small molecule inhibition of DYRK1B was proposed to be a promising approach to target GLI1-dependent cancers resistant to SMO inhibitors." (PMID 35163655, 2022). "Taken together, these data indicate that the activation of RAS/MAPK provides a novel way for cancer cells to evade SMO inhibition." (PMID 35163655, 2022). "Amongst these cancers is medulloblastoma (MB), which is the most common cancer that is predominantly treated with inhibitors of the smoothened (SMO) protein such as vismodegib or sonidegib." (PMID 35327484, 2022). "The principal mechanism of action of these drugs is the inhibition of Smoothened (SMO), a transmembrane protein involved in Hh signal transduction, that plays a role in both cellular differentiation and cancer development." (PMID 35775005, 2022). "The SMO, Gli1, and Shh played a crucial role in the Hedgehog signaling pathway on the progress of cancer." (PMID 36246980, 2022). "Dual-specificity tyrosine-phosphorylation-regulated kinase 1B (DYRK1B) was identified as a critical player in both sensitive and resistant cancers to SMO inhibitors." (PMID 35163655, 2022). "Currently, there are two FDA-approved SHH/Smoothened (SMO) inhibitors (SMOi: vismodegib and sonidegib) for treating BCCs and other cancer types in which SHH pathway activity is elevated." (PMID 36688010, 2022). "The SMO transduced signals to other proteins by interacting with Ptch, and abnormal expression of SMO promoted the cancer progression." (PMID 36246980, 2022). "GLIA-dependent transcription can additionally be induced and upregulated in cancer cells in a SMO-independent manner via crosstalk with and integration of oncogenic signaling and epigenetic cues." (PMID 35990601, 2022). "This is the first study to perform a comprehensive analysis of the relationship between the SMO gene mutation status and the clinical outcomes of patients who received ICI-treatment across multiple cancer types." (PMID 36405701, 2022). "The first approach is to develop novel and potent second-generation SMO inhibitors that retain their anti-cancer activities even in the presence of the resistance-conferring mutations." (PMID 35163655, 2022). "The investigation of small-molecule agents targeting the Hedgehog pathway in cancer continues to be an active research area, which is mainly directed to Hedgehog ligands, SMO or GLIs." (PMID 34959397, 2021). "Over the last decade, targeted therapies such as anti-SMO (smoothened protein) therapies for the treatment of BCC have emerged as a viable strategy for locally advanced periocular malignant tumours." (PMID 34198863, 2021).
cancer (continued). "Variable success using SMO inhibitors has been demonstrated across a variety of different cancer types in preclinical models and clinical models." (PMID 34113570, 2021). "SMO inhibitors have proven to be effective in treating a wide range of malignancies in clinical settings, especially in cancers such as BCC that are heavily dependent on Hh-GLI signaling." (PMID 34572373, 2021). "Despite their limitations, SMO antagonists are in new clinical trials for various cancers, either as mono- or combined therapy." (PMID 34445078, 2021). "From here on we focused on 4s to explore the molecular mechanism of these effects in cancer in HH-dependent cell lines with a high expression of SMO." (PMID 34445078, 2021). "Recently, the application of GLI1 to overcome anti-SMO resistance in several cancers has spurred great interest." (PMID 33637972, 2021). "Several HH inhibitors were tested in clinical trials for the treatment of different cancer entities, mainly with the focus on SMO inhibition." (PMID 34333666, 2021). "Since then, advances have been made for new SMO antagonists due to the development of resistance to vismodegib and also due to low responsiveness in some types of HH-driven cancers." (PMID 34831357, 2021). "Expression of GLI2ΔN results in a constitutively active GLI signaling cascade even in the presence of SMO inhibitors, providing an important mechanism for resistance to SMO inhibitors in cancer." (PMID 34639011, 2021). "Of note, genetic as well as pharmacologic inhibition of CSNK1D efficiently represses oncogenic GLI activity in cancer cells resistant to FDA-approved HH pathway inhibitors targeting the essential HH effector SMO." (PMID 34439381, 2021). "UCHL5 positively regulates Hedgehog signaling by removing ubiquitination of Smoothened, Frizzled class receptor (SMO) protein in cancer cells." (PMID 33928122, 2021). "Typically, canonical activation of the Hedgehog signaling pathway occurs in cancers with mutations in PTCH1 and SMO, which are often responsive to SMO antagonists." (PMID 34611482, 2021). "Melanomas and carcinomas of the prostate have further demonstrated a need for elevated Hh-Gli signaling, since inhibition by cyclopamine (a SMO inhibitor) can result in reduction for these types of cancers." (PMID 34113570, 2021). "Studies on chemoresistant cancer cells suggested that JNK was activated by SMO through Gβγ and stimulated GLI activity, consequently contributing to chemoresistance." (PMID 32670287, 2020). "We therefore analyzed the methylation status of CpG island 1 of the SMO gene in 33 cancer cell lines using the MSP and BSP methods." (PMID 32784501, 2020). "Increased expression of miR-324-5p has significant inhibitory effect on SMO and GLi-1 and limits cancer stemness of cells." (PMID 33489917, 2020). "Different SMO expression patterns in the cancer cell lines led us to characterize SMO gene regulatory elements." (PMID 32784501, 2020). "miR‐326 was predicted to target SMO that promotes cancer proliferation and metastasis by stimulating Hedgehog signal." (PMID 32743904, 2020). "EMSA analysis identified binding sites for the transcription factors, SP1, AP1, CREB, and AP-2α, which likely play an important role in SMO transcriptional activity in cancer cells." (PMID 32784501, 2020). "Smoothened (SMO) belongs to the Hedgehog (HH) signaling pathway, which regulates cell growth, migration, invasion and stem cells in cancer." (PMID 32962123, 2020). "Oncogenic activation of the Hh pathway—for example, as a result of mutations in SMO and SUFU—is required for the progression of some cancers." (PMID 32053600, 2020). "Ten clones of the amplified region of the putative SMO promoter for each cancer cell line were sequenced, and methylation status was established for three CpG islands in this region using bisulfite sequencing." (PMID 32784501, 2020).
cancer (continued). "Studies in LMS and other types of cancers using LDE225 demonstrated that targeting SMO is sufficient to suppress the pathogenesis of these aggressive tumors." (PMID 33396427, 2020). "It was observed that SMO expression is directly proportional to the stages of cancer so its level of expression can be used as an independent biomarker for liver postoperative metastasis to liver." (PMID 33489917, 2020). "Mutant inactivating mutations (loss of function) in PTCH1, PTCH2, or SUFU, the activation of mutations in SMO (gain of function) or the amplification of GLI2 lead to the random activation of the expression of target genes in Hh, causing cancer." (PMID 33066274, 2020). "The current clinical impact of SMO antagonists has been emphasized recently in cancer therapy, especially for a variety of solid tumors." (PMID 32962123, 2020). "The HH pathway drives oncogenesis in many cancers, and strategies targeting this pathway have been developed, most notably through inhibition of SMO, which is a key step involved in the regulation of the seven-transmembrane oncoprotein." (PMID 32784501, 2020). "Variable success using SMO inhibitors has been demonstrated in preclinical models and clinically, in a variety of different types of human cancers." (PMID 32185127, 2020). "Here, current studies pertaining to the oncopathogenic roles of SMO and its inhibitors in cancer therapy are reviewed." (PMID 32962123, 2020). "In cancer, the Hedgehog molecule SMO interacts directly or indirectly with several molecules, including MMPs, BMP4, Rho, CCN1, etc.." (PMID 32962123, 2020). "In other cancers caused by ligand-independent SHH signaling, tumorigenesis can arise from activating SMO mutations or inactivating SUFU mutations." (PMID 32957513, 2020). "A hypermethylated SMO promoter was identified in several cancer cell lines suggesting an important role for epigenetic silencing of SMO expression in certain cancer cells." (PMID 32784501, 2020). "SMO antagonists have been approved for clinical use or clinical trials in treating a variety of cancers." (PMID 32962123, 2020). "This study identified a stronger expression of SMO and Gli1 in borderline and malignant tumor tissues compared with normal ovarian epithelial or benign tumor tissues." (PMID 31261739, 2019). "They further raise the possibility of targeting the PI3K/mTOR axis as a promising therapeutic approach in HH driven cancers that are resistant to SMO inhibitors." (PMID 31492956, 2019). "The critical role of the Hh pathway in several cancers, combined with the limited success of SMO-specific antagonists in MB and other Hh-dependent cancers, motivated us to search for Hh pathway modulators with a different target profile." (PMID 31539380, 2019). "Among tumors with dysregulated Hh pathway signaling, some are sensitive to SMO antagonists, making SMO a promising anti-cancer therapeutic target." (PMID 31539380, 2019). "Despite the growing evidence for the role of the Hh pathway in various cancers, the current Hh targeted therapies in clinical trials are limited to SMO inhibitors." (PMID 31394751, 2019). "A detailed understanding of the molecular signals and mechanisms conferring SMO-independent GLI activation in cancer cells is, therefore, of critical importance for the development of novel and efficacious drugs." (PMID 30991683, 2019). "Taken together, these findings support the concept of the type-II protein kinase inhibitor chemotype being broadly compatible with SMO antagonism and suggest the robustness of concurrent inhibition of several cancer related pathways in SMO-dependent cancers." (PMID 31539380, 2019). "As a result, only a fraction of Hh-MB patients respond well to the SMO antagonists, and acquired drug resistance or cancer relapse rates are high." (PMID 31539380, 2019). "Other cancer stemness-related genes, except for EphB-1 and SMO, were downregulated to different extents by 20% to 30%, by extract or physciosporin at 10 μg/mL." (PMID 31795147, 2019).
cancer (continued). "Non-canonical GLI regulation by oncogenes has been also related to the development of resistance toward SMO inhibitors in cancer." (PMID 31244888, 2019). "While TGF-β is important for SMO-mediated cancer development, its role in the induction of GLI2 and GLI1 expression by inhibition of PKA activity has also been reported." (PMID 31202261, 2019). "In this review we will focus on additional modes of GLI activation in cancer and cancer stem cells (CSCs) that occur independently of SMO." (PMID 31244888, 2019). "Cyclopamine binds to the hydrophobic core of SMO, and it has been used in a large number of in vitro studies as a selective SMO inhibitor with antitumor activity in a number of cancer types." (PMID 31027259, 2019). "Aberrant HH signalling in cancer has led to the development of smoothened (SMO) inhibitors that target HH upstream components, thereby blocking target gene transcription." (PMID 31492956, 2019). "For example, SMO has critical roles in the HH and is a drug target in the treatment of various cancers." (PMID 31898580, 2019). "To apply this strategy to the Hh-dependent cancers, we searched for anti-SMO activities of existing approved or withdrawn drugs, with a specific focus on drugs with known activity against other cancer-related targets." (PMID 31539380, 2019). "As the first major company to develop an HH pathway programme, in collaboration with Curis Inc., it would have been in their interest to find evidence supporting the optimistic view that SMO inhibitors would be efficacious in 25% of human cancer." (PMID 30068568, 2018). "Of note, DYRK1B has been recently identified as a possible therapeutic target to overcome resistance towards SMO inhibitors in GLI-dependent cancer cells." (PMID 30558232, 2018). "Several factors, including limitations in the model systems used, the experimental designs and overinterpretation of marginal results, conspired to present unrealistic expectations regarding the potential impact of SMO inhibitors on human cancer." (PMID 30068568, 2018). "The increasing number of clinical trials using SMO inhibitors focus on the importance of targeting SMO in cancer." (PMID 30558232, 2018). "Hedgehog pathway inhibition has been proven to be an effective anti-cancer therapeutic strategy and the inhibitors or small molecular modulators for Hh/Gli signaling target on SMO and Gli1." (PMID 29249966, 2017). "Several HH inhibitors have been tested in clinical studies for the treatment of different cancer entities, with the focus being mainly on SMO inhibitors." (PMID 28418873, 2017). "Although miR-338-3p has been shown to suppress cell migration and invasion by targeting SMO, and reduced expression of miR-338-3p is a frequent event in a variety of cancers, the involvement of miR-338-3p in EMT has yet to be investigated." (PMID 29069716, 2017). "Another study dealing with human pancreatic cancer revealed an inhibitory effect on tumorigenic cancer stem cells through the combined blockade of HH and mTOR signaling using SMO and mTOR inhibitors together with standard chemotherapy." (PMID 28122581, 2017). "Currently, vismodegib and many other SMO inhibitors are being investigated in clinical trials in a range of advanced cancers." (PMID 26911235, 2016). "We therefore turned our focus to kinases as well established therapeutic targets to identify druggable effectors involved in promoting both canonical and SMO-independent GLI activation in cancer." (PMID 26784250, 2016). "Various molecular cues and genetic alterations responsible for SMO-independent GLI activation in cancer cells have been identified." (PMID 26784250, 2016). "The limitation of SMO antagonists relates to the activation of the GLI factors independently of SMO in certain cancers." (PMID 27548161, 2016). "The sheer number of clinical trials using SMO inhibitors highlights the importance of pharmacological targeting of SMO in cancer." (PMID 26891329, 2016).